VHL (von Hippel-Lindau tumor suppressor)
Diseases named in the same sentence as VHL in open-access papers (continued):
Sharing a sentence is not in itself a finding about the gene and the disease.
renal carcinoma (continued). "Many sources give evidence that HIF-2α, and not more intensively studied HIF-1α, acts as regulator in VHL-defective renal carcinomas." (PMID 29560117, 2018). "It has been demonstrated that PKM2 hydroxylation is crucial to HIF-1α transactivation in VHL-null RCC4 renal carcinoma cells at 1% O2 but not at 0.1% O2 levels." (PMID 30216369, 2018). "We also have not identified methylation of the VHL gene, although NotI-microarray hybridization revealed high levels of changes in this gene (47%) in renal cancer." (PMID 27725787, 2016). "Similarly, miR-1826 that is significantly downregulated in renal cancer tissues acts as tumor suppressor agent promoting apoptosis and cell cycle arrest by knockdown of CTNNB1 (beta-catenin) and MEK1 genes in VHL-inactivated ccRCC cells." (PMID 28326269, 2015). "In our study, lung metastases derived from LM2-4luc (triple-negative breast cancer cells that secrete high levels of VEGF and IL-8), but not SN12luc (VHL-wild-type renal cancer cells that secrete low levels of VEGF and IL-8), responded to VT treatment." (PMID 25851538, 2015). "PLD activity in renal cancer cells lacking VHL was recently reported to be involved in the expression of HIF." (PMID 25361009, 2014). "The significance of the VHL-HIFα interaction has been confirmed by a study which showed that transfection of wild type VHL in renal carcinoma cell lines lacking expression of the VHL gene was sufficient to suppress tumor growth." (PMID 22325146, 2012). "In this study, we used cultured human primary renal cancer cells and RCC cell lines including 786-0 (VHL-mutant) and Caki-1(VHL-normal) to study the role of Epo/EpoR pathway on cell proliferation, apoptosis, invasiveness, and sensitivity to anti-tumor drug Sunitinib in RCC cells." (PMID 23028796, 2012). "In this report, we found that NVP-BEZ235 inhibited the growth of VHL -/- 786-0 as well as VHL+/+ Caki-1 cells both in vitro and in vivo, suggesting that NVP-BEZ235 blocks the growth of renal cancer cells regardless of their VHL status." (PMID 21791089, 2011). "There are no direct studies of changes in Beclin1 in renal cancer, though small molecule inhibition of VHL (von Hippel Landau) in cancer cells induced autophagy and reduced growth." (PMID 22039439, 2011). "In agreement, endogenous HIF-1α protein levels were not downregulated by zinc in the RCC4 VHL-null renal carcinoma cells either in aerobic condition nor following cobalt treatment." (PMID 21179202, 2010). "Wild-type and various mutant VHL proteins representing VHL disease subtypes were stably expressed in 3 VHL-negative renal carcinoma cell lines." (PMID 19602254, 2009). "Expression of Type 1 VHL mutants in RCC10 and 786-O renal carcinoma cells failed to restore an epithelial morphology, unlike wild type VHL and the majority of type 2 VHL mutants." (PMID 19602254, 2009). "The von Hippel-Lindau tumour suppressor protein (VHL) is frequently absent in renal carcinoma tissues." (PMID 16404428, 2006). "Lack of the VHL protein and somatic alterations in the VHL gene are found in about half of conventional renal carcinomas." (PMID 16404428, 2006). "In contrast, Maher's group used an array of 558 genes and found CCND1 upregulated in a VHL mutant renal cancer cell line (RCC4), but it was not regulated by hypoxia." (PMID 15026807, 2004). "To dissect the mechanism of lipid deposition in renal cancer cells, we first evaluated the ability of a panel of three VHL (−/−) cancerous (786-O, A498 and OS-RC-2), three VHL (+/+) cancerous (ACHN, Caki-1 and SN12PM6) and one non-tumorigenic (HK-2) cell lines to make lipid droplets." (PMID 38263248, 2024). "We also observed binding of HIF-2α in HKC-8, RCC4 and 786-0 cells in the published ChIP-seq data and wondered whether this isoform could contribute to PKD1 regulation under certain circumstances, e.g. in renal cancer, when HIF-2α is released by defective VHL protein." (PMID 37206967, 2023).
renal carcinoma (continued). "However, while subsequent studies attributed the high expression of CA IX in renal cancer to mutations in the VHL gene, CA XII expression only exhibited a strong trend and not an unequivocal relationship with VHL mutation status." (PMID 35582034, 2021). "Therefore, dysfunctional VHL leads to stabilization of HIFs irrespective of oxygen availability, thereby contributing to the development and progression of renal cancer." (PMID 31690629, 2020). "We also note that since most non-hereditary ccRCCs are mutant for VHL, these results may be relevant to the management of this much larger group of renal cancers." (PMID 27682873, 2017). "Thus, the most likely mechanism for the resistance of VHL-defective renal cancer cells to 2DG-ABT therapy is that in the absence of VHL, IGF1R expression is stabilized, thus activating AKT." (PMID 27460078, 2016). "STAT3 also inhibits HIF-1α degradation through competition with Von Hippel-Lindau tumor suppressor (pVHL) for binding to HIF-1α, thus stabilising HIF-1α protein levels in tumor cells, and p-STAT3 is a potential regulator of HIF-1α-mediated VEGF expression in renal carcinoma cells." (PMID 26501341, 2015). "Additionally, using a VHL negative renal cancer cell line, 786-O, we found significantly increased expression of miR-21 as compared to HK2 proximal tubular epithelial cells." (PMID 22685542, 2012). "Therefore, VHL is not a specific biomarker for renal cancer." (PMID 35562974, 2022). "However, in animal models, VHL deletion alone does not effectively induce renal carcinoma." (PMID 35096263, 2022). "However, while these findings indicate that HIF-2α removal is sufficient to block growth of VHL-associated renal tumors, it is not clear whether HIF-2α dysregulation alone can lead to the initiation of renal carcinomas." (PMID 17598890, 2007). "VHL, which regulates HIF-1α and 2α and other types of cancer-related genes, has been shown to be extensively absent in renal cancer cells." (PMID 34604067, 2021). "This alteration was not seen in two other renal cancer cell lines (RCC4 and 786-0 −/+ VHL) but a similar change was seen in vivo in 12/15 matched normal and RCC tissue samples." (PMID 23970118, 2013). "In the present study, we show a significant increase in miR-21 expression in the VHL positive ACHN and Caki-2 renal cancer cells compared to normal proximal tubular epithelial cells." (PMID 22685542, 2012). "A requirement of both pVHL isoforms 1 and 3 or other renal cancer-specific ubiquitin ligase, as suggested by the observation that MYBBP1A is ubiquitinated in the absence of VHL, could explain this discrepancy." (PMID 30781655, 2019).
pheochromocytoma (168 papers, 2004 to 2026). "VHL type 1, which is characterized by a low risk of pheochromocytoma, is typically associated with pathogenic truncating variants that severely disrupt the folding of the VHL protein, as well as with large deletions." (PMID 40427061, 2025). "The prevalence of pheochromocytomas was 20% (95% CI: 15–25%), with a higher incidence observed in patients with specific VHL mutations." (PMID 40937003, 2025). "This case report highlights a pathogenic variant in the VHL gene c.463+4C>G associated with bilateral adrenal tumors and a histologically proven pheochromocytoma." (PMID 40051608, 2025). "Germline mutations in VHL are associated with hemangioblastomas in the brain and spinal cord, renal cell carcinoma in kidney, pancreatic neuroendocrine tumors, pheochromocytoma/paragangliomas, and other tumors in different parts of the body." (PMID 40649858, 2025). "Such mutations are common in certain pheochromocytomas, paragangliomas, and some VHL-associated pNETs." (PMID 41300999, 2025). "This was in contrast to VHL variants in other tumor types, which typically scored neutrally, with the exception of variants in pheochromocytomas and pancreatic neuroendocrine tumors (PNETs)—extrarenal tumors also linked to germline VHL mutations." (PMID 38969834, 2024). "On the other hand, VHL disease type 2 (with phaeochromocytoma) is associated with missense mutations at pVHL protein binding sites, causing local defects." (PMID 39272694, 2024). "Carriers of germinal VHL mutations have an increased prevalence of kidney cysts and ccRCC as well as hemangioblastoma, pheochromocytoma and pancreatic neuroendocrine tumors." (PMID 37489462, 2023). "Patients with missense pathogenic variants occurring outside of functional domains in the VHL gene had a higher risk of pheochromocytoma; this was protective against the development of CHB." (PMID 35475554, 2022). "One example is the classic Type 2c VHL mutant V84L, which is associated solely with pheochromocytoma in most patients but in some cases, vascular tumors, including the possibility of spinal hemangioblastoma, and renal cysts are observed." (PMID 36040300, 2022). "Von Hipper Lindau (VHL) has the highest mutation frequency among the genes associated with pheochromocytoma." (PMID 33828526, 2021). "Germline VHL mutations associate with classical VHL disease and represent genetic susceptibility for pheochromocytoma." (PMID 34899081, 2021). "In this paper, we found that authenticated VHL mutation p.Arg167Gln is not only associated with bilateral pheochromocytoma but lung carcinoid and neuroendocrine tumor of pancreas, which have not been reported." (PMID 34923986, 2021). "In order to further prove the clinical significance and application value of these proteins, we collected the tumor tissues of four patients with VHL mutation pheochromocytoma to verify the expression of these genes in vivo." (PMID 33828526, 2021). "A study from Turkey reported 18 RET C634G mutations in 88 individuals, while another study reported VHL mutations in two pheochromocytoma patients." (PMID 33777662, 2021). "We reported a rare case of atypical VHL syndrome with authenticated VHL mutation at p.Arg167Gln, that was associated with not only bilateral pheochromocytoma but also lung carcinoid and neuroendocrine tumor of pancreas." (PMID 34923986, 2021). "To study the influence of VHL mutations on the development of pheochromocytoma, we constructed stable VHL-KD PC12 cell line model and evaluated the efficiency of VHL-KD at mRNA and protein levels." (PMID 33828526, 2021). "We report a Caucasian male with a family history of pheochromocytoma and the synonymous VHL mutation c.414A > G (p.Pro138Pro)." (PMID 32106822, 2020). "For example, a retrospective study that included 63 VHL patients from two large VHL kindreds (family 1: Y112H mutation and family 2: Y98H mutation) with pheochromocytoma/paraganglioma found that pheochromocytoma expressivity differed by genotype." (PMID 31620170, 2019).
pheochromocytoma (continued). "The subsequent loss of the tumor suppressive function of VHL secondary to inactivation of both alleles has been postulated as the basis for the development of neoplasms such as HB, pheochromocytomas, and RCC in patients with VHL." (PMID 28868236, 2017). "Germline mutations in the succinate dehydrogenase (SDHA, SDHB, SDHC, SDHD, SDHAF2) or Von Hippel-Lindau (VHL) genes cause hereditary paraganglioma/pheochromocytoma." (PMID 28099933, 2017). "About 2530% of pheochromocytomas/paragangliomas develop under the conditions of a hereditary tumor syndrome a third of which are caused by mutations in the VHL gene." (PMID 28187001, 2017). "Two patients with NET had mutations in MEN1 gene, one patient with pheochromocytoma had a pathogenic VHL mutation in exon 3, and one patient with paraganglioma had a variant of uncertain significance in SDHB c.287-3C>G." (PMID 29262620, 2017). "Usually in pheochromocytoma the missense variations which account for 80–95% of mutations in Type 2 VHL leave pVHL with some residual activity which is in contrast to the possibility of complete abrogation of Elongin C binding in our case." (PMID 27069690, 2016). "Somatic mutations in sporadic pheochromocytoma/paraganglioma has been identified in VHL, RET, SDHB, and SDHD but their frequency was reported to be low." (PMID 26347711, 2015). "It showed a mutation in the VHL ex.1 p.Y112 C gene responsible for the hereditary form of phaeochromocytoma and confirming von Hippel-Lindau syndrome." (PMID 26268347, 2015). "VHL mutations can also produce pheochromocytomas and paragangliomas, but the role of VHL in the development and homeostasis of the sympathoadrenal system is still not well understood." (PMID 25385837, 2014). "Further studies should be performed on a larger group of pheochromocytoma patients with a VHL or RET gene mutation to confirm these observations." (PMID 24523932, 2014). "Genotype-phenotype correlation studies have shown that VHL type 1 families frequently harbor VHL deletions or nonsense mutations, whereas families at risk for developing pheochromocytoma (type 2 families) almost invariably present with VHL missense mutations." (PMID 24899893, 2014). "It has been proposed that VHL-associated pheochromocytoma tumorigenesis is related with an abnormal extracellular matrix formation and to upregulation of tyrosine hydroxylase, leading to increased catecholamine synthesis." (PMID 24899893, 2014). "For instance, the presence of hemangioblastomas (suggestive of von Hippel-Lindau) or medullary thyroid carcinoma along with pheochromocytoma (suggestive of MEN 2A) strongly implies mutations in VHL or RET gene, respectively." (PMID 24899893, 2014). "For instance, in VHL disease-associated pheochromocytoma, codon 167 of VHL gene appears as a first target, since missense mutations in this codon are strongly associated with pheochromocytoma development." (PMID 24899893, 2014). "Mutations in VHL and SDHx genes have been shown to induce pseudohypoxic states that induce the development of paragangliomas/pheochromocytomas." (PMID 24899893, 2014). "In 2006, a study comprising a larger number of patients with pheochromocytoma/paraganglioma showed that 33% of the patients carried germline mutations in one of the following genes: VHL, RET, NF1, SDHB, and SDHD." (PMID 24899893, 2014). "Various missense mutations in the VHL gene have been reported among patients with familial bilateral pheochromocytoma." (PMID 23626751, 2013). "The clearest genotype-phenotype correlation is exemplified by type 2 VHL, typically characterized by a VHL missense mutation and presence of pheochromocytomas." (PMID 23384121, 2013). "We describe the details of three members a family who presented with only bilateral pheochromocytoma, where VHL gene mutations were eventually detected when the testing system became available as part of a routine screening of patients with PCC." (PMID 23626751, 2013).
pheochromocytoma (continued). "Type 1 VHL is more frequently characterized by a VHL truncating mutation and absence or rare occurrence of pheochromocytomas." (PMID 23384121, 2013). "A glycolytic profile unifies a group of pheochromocytomas and paragangliomas (PHEOs/PGLs) with distinct underlying gene defects, including von Hippel-Lindau (VHL) and succinate dehydrogenase B (SDHB) mutations." (PMID 22859959, 2012). "We identified four families with pheochromocytoma-dominant VHL phenotypes who carry stop codon mutations." (PMID 20560986, 2011). "Among them, a missense mutation of the VHL gene was identified in 3 tumors (13%) which were considered as pheochromocytomas associated with a type 2c VHL disease." (PMID 20454689, 2010). "To evaluate the link between hypoxia and Warburg effect, we studied mitochondrial electron transport, angiogenesis and glycolysis in pheochromocytomas induced by germ-line mutations in VHL, RET, NF1 and SDH genes." (PMID 19763184, 2009). "The patient, her father, and daughter remain in a periodical screening program for VHL disease for early detection of other VHL associated tumours, but especially pheochromocytomas." (PMID 17922902, 2007). "The diagnosis of VHL disease was now proven based on the positive family history for pheochromocytoma and the mutation in the VHL gene." (PMID 17922902, 2007). "Somatic VHL gene alterations are implicated in the pathogenesis of MEN2-associated pheochromocytomas, possibly through accumulation of RET protein." (PMID 16707008, 2006). "Our findings link pheochromocytomas with mutations in distinct genes—VHL,SDHB, and SDHD—and suggest that mitochondrial complex II inhibition contributes to development of pheochromocytomas with VHL mutation." (PMID 16103922, 2005). "This prompted us to examine the link between pheochromocytomas with VHL and SDH mutations in our series by first determining the protein expression of the catalytic unit of complex II, SDHB." (PMID 16103922, 2005). "VHL is named after its role in von Hippel-Lindau disease (VHL), an inherited disorder that predisposes individuals to pheochromocytomas and other tumors." (PMID 16103922, 2005). "We show here that pheochromocytomas with VHL and SDHB or SDHD mutations form a tight cluster with a clear hypoxia and reduced oxidoreductase signature." (PMID 16103922, 2005). "Transcription profiling of a large series of primary pheochromocytomas reveals that tumors with VHL and SDH mutations are closely linked." (PMID 16103922, 2005). "von-Hippel Lindau (VHL) disease, a familial cancer syndrome that predisposes individuals to clear cell renal carcinoma as well as other tumor types, including hemangioblastomas and pheochromocytomas, is caused by inherited mutations in the VHL tumor suppressor gene." (PMID 39883230, 2025). "This case highlights three pivotal clinical insights for managing VHL syndrome with multisystem involvement: First, VHL-associated pathologies (e.g., pheochromocytoma-driven hypertension) may confer unique susceptibility to aortic dissection." (PMID 41164131, 2025). "The VHL gene, located on the short arm of chromosome 3 (3p25.3), has over 1,500 identified pathogenic variants in patients with VHL disease, with 20% of these being de novo pathogenic variants, as observed in both PGLs and pheochromocytomas." (PMID 39735644, 2024). "Finally, continued research in these areas has the potential to improve outcomes for VHL patients with pheochromocytoma and other associated tumors." (PMID 38344311, 2024). "According to the predisposition to pheochromocytoma, VHL subclasses have been classified." (PMID 36902045, 2023).